BLM (BLM RecQ like helicase)
Diseases named in the same sentence as BLM in open-access papers (continued):
Sharing a sentence is not in itself a finding about the gene and the disease.
breast carcinoma (continued). "Therefore, in order to resist HJNO soppressing BLM helicase, the mRNA and protein levels of BLM helicase in the MDA-MB-435 breast cancer cells increased through feedback when treated with HJNO." (PMID 31660888, 2019). "Interestingly, most of these key repair genes, including BRCA1, RAD51, RAD54L and BLM, were also identified in this study as E2F1 targets in breast cancer." (PMID 27666291, 2016). "Based on their biological functions BLM, RECQL4 and DCLRE1C all represent attractive susceptibility genes, although to date clearly deleterious, breast cancer related mutations have not been reported in any of them." (PMID 22737080, 2012). "Therefore, we tested LN229- WT, RQ4 KO or BLM KO cells responses to WP744, the 4’-O-benzylated doxorubicin analogue, inhibiting DNA topoisomerase II and triggering apoptosis in breast cancer, acute myeloid leukemia, neuroblastoma cells and human glioma stem cells." (PMID 41023983, 2025). "Conditional BLM knockout mice bearing heat shock promoter cre transgene (HS-cre), prostate-specific antigen promoter-cre transgene (PSA-cre), and ovine beta-lactoglobulin promoter-cre transgene (BLG-cre) develop different types of mammary tumors, i.e., adeno-myoepithelioma and adenocarcinoma." (PMID 33777104, 2021). "The BLM deletion was genotyped in relatives of the affected proband and identified two additional carriers of deletion but none were affected with breast cancer and an (obligate) non-carrier of this deletion had had breast cancer diagnosed at age 42 years." (PMID 28302160, 2017).
Werner syndrome (37 papers, 2007 to 2025). "Loss of function of three of these results in cancer predisposition disorders Bloom's syndrome (BS, defective in BLM), Werner's syndrome (WS, defective in WRN) and Rothmund Thomson syndrome (RTS, defective in RECQ4)." (PMID 20808892, 2010). "Alterations in BLM and WRN, the human homologs of Sgs1 result in Bloom and Werner syndromes, respectively, characterized by cancer predisposition and developmental defects." (PMID 31936378, 2020). "A deficiency in either BLM or WRN is the cause of two genetic diseases called respectively Bloom and Werner Syndrome." (PMID 26136769, 2015). "Human diseases leading to premature ageing phenotypes, such as Bloom and Werner syndromes, originate from dysfunctions in two RecQ helicases involved in DNA recombination, BLM, and WRN." (PMID 25402830, 2014).
Fanconi anemia (24 papers, 2009 to 2025). Fanconi anemia (FA) is a hereditary DNA repair disorder characterized by progressive pancytopenia with bone marrow failure, variable congenital malformations and predisposition to develop hematological or solid tumors. "We discovered that loss of the BLM complex rescues survival of Fanconi anemia deficient cells upon generation of DNA damage by reagents that generate ICLs." (PMID 29089570, 2017). "We also found specific upregulation of genes of the Fanconi anemia pathway, in particular FANCM, FANCD2 and FANCI, which encode known interaction partners of BLM." (PMID 35099000, 2022). "For example, methylated RUNX1 has increased transcription activation potency, whereas poly (ADP)-ribosylation of RUNX1 and RUNX3 enables interaction with the helicase BLM (Bloom syndrome protein) in response to DNA damage in the context of Fanconi anemia." (PMID 34421907, 2021). "WES revealed that HMCLs displayed frequent mutations in Fanconi anemia genes (PALB2 [12%], FANCI [12%], FANCA [9%], FANCD2 [9%], BRCA2 [9%]) as well as in helicases (such as RECQL4, 15%, and BLM, 15%) and epigenetic modifiers (e.g., TET2, 15% and SETD2, 6%)." (PMID 30545397, 2018). "We identify the BLM helicase complex as a suppressor of Fanconi anemia phenotypes in human cells, demonstrating that systematic screening approaches can be used to reveal genetic viable interactions for DNA repair defects." (PMID 29089570, 2017). "Here the authors use parallel genome-wide screens that identify the BLM helicase complex as a suppressor of Fanconi anemia phenotypes." (PMID 29089570, 2017). "Studies in chicken DT40 cell lines provided early experimental data suggesting interplay of BLM with the Fanconi Anemia (FA) pathway important for the response to interstrand cross-links (ICL) and maintenance of genomic stability." (PMID 25906194, 2015). "In the last few years, a direct role for Fanconi anaemia (FA) pathway and RecQ helicase Bloom syndrome protein (BLM) has been demonstrated in the prevention and resolution of UFBs." (PMID 24083238, 2013). "Fanconi anaemias and xeroderma pigmentosa are chromosomal breakage syndromes related to BLM proteins." (PMID 20442845, 2009). "In addition, FANCD2, another Fanconi Anemia (FA) protein, is also required for CC formation, likely through promoting the recruitment of BLM to the replication stressed ALT telomeres." (PMID 31836759, 2019). "Except for the mosaic NONO mutation and homozygous DIS3L2, BLM, and BRCA2 alterations in syndromic patients (Perlman, Bloom, Fanconi anemia), all predisposing genetic changes occurred as heterozygous germline events." (PMID 40340749, 2025). "There was substantial overlap between SSTR and HR: both pathways require Fanconi Anemia Repair, nucleotide excision repair (NER), and strand displacement activities, which is driven by mutual reliance on FA proteins, members of the TFIIH complex, and the BLM helicase." (PMID 32355159, 2020). "Among DNA repair genes, we detected a high presence of members of the Fanconi Anemia Complementation Group (FANCC, FANCD2, FANCG, FANCA, and FANCE), which participate in homologous recombination DNA repair, and genes involved in double-strand break repair (BRCA2, BRIP1, BARD, BLM, CHEK2, and PALB2)." (PMID 30487452, 2018).
Rothmund-Thomson syndrome (22 papers, 2006 to 2025). "For example, deficiencies in RecQ family helicases BLM/RECQ2, WRN/RECQ3, and RTS/RECQ4 lead to Bloom, Werner, and Rothmund-Thomson syndromes, respectively." (PMID 34912850, 2021). "Several syndromes are associated to the RecQ genes’ family including Werner syndrome (WS), Bloom syndrome (BS) and Rothmund Thomson syndrome (RTS), that are respectively associated with pathogenic variants in RECQL2/WRN, RECQL3/BLM, and RECQL4 genes." (PMID 31829210, 2019). "Sgs1 is a RecQ family DNA helicase and a homolog of the human BLM, WRN, and RECQL4 proteins that are mutated in Bloom's, Werner, and Rothmund Thomson syndromes, respectively." (PMID 23271978, 2012). "There are five RecQ helicases in humans, including the WRN, BLM, and RecQ4 proteins that are defective in Werner (WS), Bloom (BS), and Rothmund-Thomson syndromes (RTS), respectively." (PMID 16412221, 2006). "Of the five human RecQ families, three are genetically linked to cancer syndromes and premature diseases, such as Bloom’s syndrome (BLM gene mutations), Werner’s syndrome (WRN gene mutations), Rothmund-Thomson syndrome (RTS), RAPADILINO, and Baller-Gerold syndrome (caused by mutation of RECQ4)." (PMID 34381789, 2021). "Although no hereditary disease has been linked with the RECQL gene to date, mutations in three of five RecQ genes, BLM, WRN and RECQ4, lead to Bloom, Werner, and Rothmund-Thomson syndromes, respectively, and are associated with cancer predisposition and/or premature aging." (PMID 25945795, 2015). "Also, Mutations in the helicases, including Bloom syndrome protein (BLM), Werner syndrome protein (WRN) and ATP-dependent DNA helicase QL4 (RecQL4) that mediate replication fork remodeling and restart can result in the development of Bloom, Werner and Rothmund-Thomson syndromes, respectively." (PMID 31717862, 2019). "Unlike BLM and WRN, which are linked to specific diseases with similar symptom clusters, mutations of the RECQL4 gene can lead to a variety of conditions, including Rothmund-Thomson syndrome (RTS), Baller-Gerold syndrome (BGS), and RAPADILINO syndrome, depending on the specific mutation involved." (PMID 40728512, 2025).
colorectal cancer (17 papers, 2010 to 2024). "BLM gene mutations are known to be associated with increased risk of developing multiple cancers including breast, colorectal cancers and endometrial cancer which is consistent with our findings and support the pathogenicity of the identified variant." (PMID 38313678, 2024). "Deleterious mutations in the BLM gene are associated with an increased risk of prostate, breast and colorectal cancers." (PMID 37169803, 2023). "The aberrant overexpression of BLM in the cytoplasm in colorectal cancers was associated the CpG island promoter hypomethylation and increased DNA damage responses." (PMID 37169803, 2023). "More recently, it was classified among deleterious germline BLM mutations with moderately increased risk for early-onset colorectal cancer." (PMID 33219493, 2022). "One study investigated polymorphisms in WRN, RMI1, and BLM in a large population-based case-control study of colorectal cancer patients and controls and found an association of BLM P868L with rectal cancer risk." (PMID 35782872, 2022). "The human genes SMC1, SMC3, NIPBL, STAG3, RNF20, FBXW7/CDC4, MRE11A, RAD54B and BLM have been found to be mutated in colorectal cancer, and together account for approximately 25% of the CIN mutational spectrum of this disease." (PMID 23382697, 2013). "Though BS patients are rare, BLM heterozygotes that carry a BLM mutation may be faced with a higher probability of developing colorectal cancer." (PMID 21050475, 2010). "RECQL1, WRN, and RECQL5 mRNA expression have been found to be lower in primary colorectal carcinoma (CRC) samples compared to normal colonic mucosa, while BLM and RECQL4 mRNA levels are increased." (PMID 35782872, 2022). "Additional studies have shown that increases in reactive oxygen species following SOD1 (Superoxide Dismutase 1) silencing and inhibition induces SL killing in colorectal cancer cells harboring defects in established CIN genes, like RAD54B, BLM, and CHEK2." (PMID 29104272, 2017). "By targeting BLM, DENND2D, PHLPP1 or MAOB, miR‐522 could boost tumorigenesis of colorectal cancer, non‐small‐cell lung cancer, glioblastoma and endometrial carcinoma, respectively." (PMID 33369228, 2021).
ovarian carcinoma (16 papers, 2015 to 2023). A malignant neoplasm originating from the surface ovarian epithelium. "Germline mutations of CHEK2 and BLM have been reported to be associated with several types of cancer, including prostate cancer, uterine serous carcinoma, and breast and ovarian cancer." (PMID 36053931, 2023). "Recently, studies have shown that increased expression of BLM is associated with platinum in ovarian cancer." (PMID 32762026, 2020). "Overexpression of BLM RecQ like helicase (BLM) is able to induce DNA damage and increase sensitivity to platinum agents in triple-negative breast cancer and ovarian cancer." (PMID 33995018, 2021). "In another study, the upregulation of Polθ and its positive correlation with expression of many DNA repair genes including TOPBP1, BLM, RAD54L, FANCI, BRCA1, FANCD2, ATAD5 was reported in HR-deficient epithelial ovarian cancer cells." (PMID 34762643, 2021). "In our case-control analyses with a non-cancer east-Asian population and non-cancer females, we found significant prevalence of PALB2, BARD1, BLM, and ATM mutations in our HBOC cohort, including patients with ovarian cancer." (PMID 32566746, 2020). "Then, we focused on genes traditionally associated with breast/ovarian cancer or other malignancies, and identified 23 missenses, 2 splicing, and 2 UTR variants mainly affecting genes involved in DNA repair, such as RAD51, RAD54B, PMS1, FANCD2, XRCC1, and BLM." (PMID 35893033, 2022). "In detail, BLM was overexpressed in ovarian cancer tissues in the seven studies." (PMID 32762026, 2020). "Not only that, but BLM expression also has a certain correlation with ovarian cancer." (PMID 32762026, 2020).
prostate carcinoma (15 papers, 2015 to 2025). A carcinoma that arises from epithelial cells of the prostate gland. "To date, there has been no documentation of circRNAs that regulate the initiation or progression of prostate cancer through the miR-27b-3p/BLM axis, and the underlying mechanisms remain undefined." (PMID 38806577, 2024). "Several reports have suggested that BLM mutations in prostate cancer increase the sensitivity of patients to PARPi_olaparib." (PMID 39009979, 2024). "Many reports have indicated that nonsense mutations in the BLM gene can increase the risk of prostate cancer." (PMID 32762026, 2020). "As a result, scientists have explored the possibility of targeting BLM to improve survival rate in breast, colon, and prostate cancers." (PMID 40728512, 2025). "In conclusion, circ_0001671 exerts an oncogenic effect in prostate cancer through the regulation of BLM by sponging miR-27b-3p, thus suggesting a novel molecular target for the treatment of PCa." (PMID 38806577, 2024). "Abnormal expression of BLM helicase has been observed in a range of cancer types, notably exhibiting elevated levels in prostate cancer (PCa)." (PMID 38806577, 2024). "Mechanistically, circ_0001671 functions as a sponge for miR-27b-3p, thereby upregulating BLM expression by attenuating miR-27b-3p activity and consequently facilitating the progression of prostate cancer." (PMID 38806577, 2024). "In prostate cancer cells, overexpression of circ_0001671 has been observed to result in elevated BLM expression." (PMID 38806577, 2024). "Using CRISPR/Cas9, they showed that BLM deletion in prostate cancer cells inhibits cell proliferation by downregulating pAKT and pRAS, which leads to increased reactive oxygen species production." (PMID 35782872, 2022). "BLM was then silenced using CRISPR/Cas9 in PC-3 prostate cancer cells to observe its effects on PC cell health, proliferation, and signaling." (PMID 31210839, 2019). "Site-directed knockout of BLM in PC-3 prostate cancer cells was performed using CRISPR/Cas9-mediated homologous recombination gene editing to confirm the effects of BLM on DEPs." (PMID 31210839, 2019). "Taken together, we have shown that Andrographolide is an effective anti-cancer compound for prostate cancer by regulating genes associated to double-strand breaks such as ATM, NBN, BRCA2 BLM, PALB2 and BLM." (PMID 30800220, 2019). "Specifically, BLM inhibition has been shown to enhance the cytotoxic activity of alkylating agents in multiple myeloma and prostate cancer cells, and it may offer therapeutic benefit in tumours that are intrinsically resistant to PARP inhibitors or radiation." (PMID 40750583, 2025). "BLM mRNA and protein expression are upregulated in prostate cancer cells compared to controls." (PMID 35782872, 2022). "One study investigated the role of BLM in prostate cancer progression." (PMID 35782872, 2022). "The interaction between BLM and EZH2 reportedly affects the occurrence and development of prostate cancer." (PMID 36750200, 2023). "Prior studies indicated that miR-27b-3p could directly target the BLM gene 3' UTR, thereby suppressing the proliferation, migration, and invasion of prostate cancer cells." (PMID 38806577, 2024). "According to the cytoplasmic staining intensity and positive staining rates, pAKT (Ser473), pPRAS40 (Thr246), and BLM expression levels were higher in prostate cancer tissue than in non-PC tissues." (PMID 31210839, 2019). "The function of BLM in tumorigenesis and tumor progression could be explained by the inhibition of apoptosis and promotion of proliferation in prostate cancer but not in normal prostate tissue." (PMID 40728512, 2025).
melanoma (13 papers, 2009 to 2025). A malignant, usually aggressive tumor composed of atypical, neoplastic melanocytes. "In order to gain information on the molecular mechanism by which HSPB8 exerts its action in melanoma, we transiently transfected mutated forms of HSPB8 (HSPB8K141E and HSPB8K141N) in BLM and A375 cells." (PMID 36400750, 2022). "As controls, we were also able to isolate melanoma cells (MV3, BLM) targeting melanoma-associated chondroitin sulfate proteoglycan (MCSP), but not HEK293T." (PMID 34829387, 2021). "Depletion of p85β, but not of p85α, reduced invadopodium formation and blocked gelatin degradation, suggesting that p85β is needed for invadopodium formation in BLM melanoma cells." (PMID 25217619, 2014). "Compared to controls or p85α silencing, p85β depletion reduced BLM cell capacity to degrade the basement membrane, confirming the need for p85β expression for BLM melanoma invasion." (PMID 25217619, 2014). "Although RAD54B, BLM and CHEK2 genes are mutated in CRC, they are also mutated in numerous additional cancers including pancreatic (~16.5% collectively), prostate (~16.7%), melanoma (~15.1%) and endometrial (~8.8%)." (PMID 26318585, 2015). "In BLM, rs401549 was associated with significantly increased risk for bladder cancer and a non-significantly increased risk for malignant melanoma." (PMID 19432957, 2009). "In this study we have studied 26 tagged single nucleotide polymorphisms (tagSNPs) in RMI1, TOP3A, and BLM and their associations with cancer risk in acute myeloid leukemia/myelodysplatic syndromes (AML/MDS; N = 152), malignant melanoma (N = 170), and bladder cancer (N = 61)." (PMID 19432957, 2009). "To address whether the canonical Smad pathway is involved in the mediation of the TGFβ effects on melanoma self-renewal, we generated specific Smad2, Smad3 and Smad4 knockout (KO) in two different melanoma cell lines, A375m and BLM, using CRISPR genomic editing." (PMID 38201651, 2024). "Interestingly, in the control, BMP-2 and nodal groups, the invading melanoma cells depicted a mesenchymal, stretched morphology, while in the antagonist groups, clusters of epithelial-like, rounded, aggregated BLM cells prevailed in the dermal part of the skin reconstructs." (PMID 29716947, 2018). "To address the role of CREPT in the malignant feature of melanoma, we examined the colony formation ability of CREPT-modified BLM cells." (PMID 31877646, 2019). "More importantly, treatment with 4‐PBA rescued imiquimod‐induced cell death of BLM and MV3 cells, suggesting that imiquimod‐induced melanoma cell death is mediated via ER stress‐dependent mechanism(s)." (PMID 26578344, 2016). "Interestingly, all melanoma cell lines and all conditions showed an activation of the PI3K signaling pathway as indicated by phosphorylated Ser473 of AKT although only BLM did not express PTEN in clearly detectable amounts (BLM is known to have a methylated PTEN promoter)." (PMID 29454361, 2018).